SOX2 (SRY-box transcription factor 2)
Diseases named in the same sentence as SOX2 in open-access papers (continued):
Sharing a sentence is not in itself a finding about the gene and the disease.
glioblastoma (continued). "In glioblastoma (GBM), miR-486-5p augments the self-renewal capacity of GBM stem cells by targeting PTEN and FOXO1, thereby inhibiting the tumor suppressor network regulated by Sox2." (PMID 40710326, 2025). "Hypoxia-inducible factor (HIF) induces the expression of both SOX2 and KLF4 in glioblastoma (GBM), which in turn upregulate CD133/15, ultimately promoting stemness expression." (PMID 38331879, 2024). "In glioblastoma, SALL2, together with SOX2, POU3F2, and OLIGO2, reprogrammed differentiated tumor cells into tumor stem cells, and also, SALL2 was one of the partners of SOX2, suggesting SALL2 may be essential for the homeostasis of NSCs in the nervous system in vivo as well." (PMID 39349437, 2024). "TRIM8 re-localizes from the cytoplasm of healthy neurons to the nucleus in GBM cells to establish a stem-like phenotype, with an increase in malignancy and glioblastoma stem cell markers, such as STAT3, SOX2, Nestin, and Nanog." (PMID 38115822, 2023). "Leveraging superenhancer profiling in glioblastoma tissues and GSCs, we identified an epigenetically upregulated gene, KLHDC8A, with expression driven by a superenhancer element located upstream of the gene with contributions from the stemness transcription factor SOX2." (PMID 36394953, 2023). "The aim of this study was to investigate the expression of four pluripotency-related genes (OCT4, NANOG, SOX2, and CARM1) in human glioblastoma (GBM)." (PMID 35274101, 2022). "The RR GBM cells were enriched with glioblastoma stem cells (GSCs) confirmed by specific marks of CD133, OCT4, SOX2, NANOG, and HER2 by Western blot with elevated CD133/HER2 population identified by flow cytometry analysis." (PMID 35314680, 2022). "2D monolayer U87 glioblastoma cells were cultured into 3D spheroid-forming conditions (neurospheres), as these are known to be much closer to the tumor than adherent cells and to recapitulate some cancer stem cell phenotype as well as including increased expression of CD133, Nanog, and Sox2." (PMID 34884812, 2021). "Furthermore, SOX2 showed strong H3K27ac activation in all glioblastoma subtypes, and its RNA expression did not significantly change in the SOX10 knockdown models." (PMID 33339831, 2020). "Radiation in GBM (glioblastoma) cells enhances the METTL3 expression and it increases the stability of SOX2 by recruiting hUR (human antigen R) and induces resistance against radiation." (PMID 33718113, 2020). "Interestingly, in glioblastoma, SOX2 and miR145 have been reported to form a negative feedback loop with one another." (PMID 28388544, 2017). "Therefore, SOX2 is a strong molecular candidate to be targeted in glioblastoma samples and the potential benefit of SOX2 targeting in the scenario of such a lethal tumor is not negligible." (PMID 27822457, 2016). "SOX2 up-regulation, altered fatty acid metabolism, and mRNA metabolism might contribute to TMZ resistance, while metformin treatment partially reverses these up-regulated genes back to original or near original levels found in parental glioblastoma cell lines." (PMID 27791206, 2016). "Thus, we speculate that SOX2+ HIF-1α+ RNApII-S2P-/low cells and HIF-2α+ cells might play different roles in the biology of glioblastoma." (PMID 26799577, 2016). "Given that HES1 oscillations are known to facilitate the transition out of quiescence, it is plausible to hypothesise that sustained, non-oscillatory SOX2 expression could prevent quiescent glioblastoma cells from reactivating, thereby impairing tumour reactivation and progression." (PMID 41142923, 2025).
glioblastoma (continued). "In addition, PVT1 regulates E74-like factor 4 (ELF4) expression by competitively binding to miR-365 and controls the stemness of GSCs via the miR-365/ELF4/SOX2 axis Thus, PVT1 may serve as a potential therapeutic target and prognostic indicator in glioblastoma." (PMID 39015773, 2024). "Indeed, exposure of glioblastoma stem-like cells to recombinant BMP7 in vitro increased SMAD1/5/8 phosphorylation, inhibited cell proliferation, stimulated glioblastoma differentiation, decreased neurosphere formation and attenuated expression of the stem-like genes Nanog, SOX2, Nestin and Olig2." (PMID 29799477, 2018). "In line with the hypoxia-induced upregulation of CD133 and nestin found in the present study, SOX-2 has previously been reported to be upregulated in response to hypoxia and SOX-2 might therefore play an important role in hypoxia-induced biology of glioblastoma." (PMID 29708435, 2018). "However, although we could detect a similar overlap in the expression pattern of Sox2, Oct4 and Nanog in ES cell-derived teratomas as in glioblastomas, teratoma cells did not express pluripotent stem cell markers in combination with NSC proteins such as Sox1." (PMID 21483788, 2011). "CTH expression in the tumor stroma/microenvironment plays a crucial role for glioblastoma formation and triggers the expression of the GSC marker SOX2 without affecting the tumoral vascular network." (PMID 37300955, 2023). "In contrast, our data support findings from a recent study that suggest widespread co-expression of SOX2, OLIG2 and ZEB1 in glioblastoma, irrespective of key driver alterations." (PMID 28945795, 2017). "Expression levels of cancer stemness marker SOX2 were reduced in treated tumor cells and SB747651A treatment significantly prolonged survival of mice with intracranial glioblastoma xenografts, while no adverse effects were observed in vivo at doses of 25 mg/kg administered 5 days/week for 8 weeks." (PMID 33727611, 2021). "However, SB747651A ́s multi-targeting of glioblastoma metabolism, mediated by GSK3 and GYS1, combined with mTOR and CREB inhibition, and a decrease of SOX2 expression, has not previously been described." (PMID 33727611, 2021). "In our culture model, a population of glioblastoma cells was able to form aggregates composed of cells with multilineage phenotype, i.e. showing expression of: CD44, Vimentin, GFAP, Nestin, Beta III-tubulin, MAP2, Fibronectin and SOX-2, but not CD133." (PMID 19216795, 2009). "Furthermore, western blot experiments (P < 0.05) were utilized to detect the protein expression, and Dazl knocked-down glioblastoma cell lines showed significantly reduced expression of stemness markers CD133, Oct4, Nanog, and Sox2, and no changes in the protein expression of beta-Catenin." (PMID 32682409, 2020). "In contrast, in human glioblastoma (GBM) cell lines CA did not down-regulate the PI3K/AKT pathway, whereas it induced proteasomal down-regulation of Retinoblastoma, Cyclin B1, SOX2 and GFAP and cell cycle arrest with only a minor induction of apoptosis." (PMID 29100552, 2017). "In contrast, SOX2+ HIF-1α+ RNApII-S2P-/low cells could neither be detected around small necroses with pseudopalisading of tumor cells, which is another type of necrosis in glioblastoma tissues, nor in the areas devoid of necrosis." (PMID 26799577, 2016).
lung carcinoma (306 papers, 2010 to 2025). "Modification or abnormal expression of SOX2 has been implicated in the occurrence, progression, invasion, and metastasis of breast and lung cancers." (PMID 41463190, 2025). "In lung cancer, stemness related to SOX2 has been linked to the release of cytokines in the TME, resulting in tumor cell plasticity and tolerance to therapy." (PMID 38275880, 2024). "Studies reported that overexpression of Oct4 and Sox2 were associated with drug-resistance, including chemotherapy, radiation therapy and target therapy in lung cancer and bladder cancer, malignant mesothelioma cells and osteosarcoma." (PMID 38822350, 2024). "In lung cancer, Sox2 is highly linked with the ‘lineage-specific survival mechanism’ in lung cancer." (PMID 38164743, 2023). "In EGFR-mutated lung cancer cells, SOX2 overexpression promotes resistance to erlotinib by repressing the expression of proapoptotic proteins BIM and BMF." (PMID 38096163, 2023). "One study revealed that overexpression of SOX2 amplifies the 3q gene, which is the most common genomic mutation in lung cancer." (PMID 38248716, 2023). "Recently, emerging data have shown that aberrant SOX2 expression is also associated with various types of cancer, including lung cancer." (PMID 35059870, 2022). "In our study, we demonstrated the aberrant upregulation of TRIB3 correlated with the lung cancer progression, which was associated with the SOX2 transcription factor activation." (PMID 35473511, 2022). "CDK1 was associated with maintenance of stem cell properties in lung cancer by interacting with SOX2, another stem cell marker in CRC, and its protein expression increases significantly from normal mucosa to dysplasia and from dysplasia to carcinoma." (PMID 36362041, 2022). "Our results further described the underlying mechanism of integrin αvβ3 and SOX2 in regulating lung cancer development, which provided new sight for target therapy in lung cancer." (PMID 35473511, 2022). "Oxidation of SOX2 at Cys265 can inhibit its transcriptional activity and make lung cancer cells with high SOX2 expression more susceptible to ferroptosis." (PMID 34796174, 2021). "Considering other tissues, a significant association was identified between the expression of Sox2 and β-catenin in cervical squamous cell carcinoma and lung carcinoma." (PMID 33112555, 2020). "In lung cancer particularly, the overexpression of SOX2 has been associated with better prognosis and survival." (PMID 30867047, 2019). "This is in contrast to a previous report which found that the expression of high levels of Sox2 was associated with malignancy in human lung cancer stem-like cells/cancer-initiating cells." (PMID 23251245, 2013). "Importantly, while SOX2 promotes tumor progression in lung cancer, it also functions as a significant biomarker linked to favorable patient outcomes." (PMID 39976818, 2025). "The aberrant upregulation of SOX2 has also been implicated in CSCs self-renewal and resistance to therapies in osteocarcoma and lung cancer patients and could be an attractive target for anti-cancer therapy." (PMID 38429272, 2024). "The chloroform fraction also inhibited the growth of the A549 spheroid by suppressing the spheroid size, inducing apoptosis, reducing the proportion of CD44 lung cancer stem cells, causing arrest at the S phase of the cell cycle, and suppressing the expression of the SOX2 and MYC genes." (PMID 37513848, 2023). "Moreover, it has been suggested that high expression of both FGFR1 and SOX2 is associated with shorter survival of lung cancer patients." (PMID 34830951, 2021). "Furthermore, the gene for a transcription factor, sex‐determining region Y‐box 2 (SOX2) was identified as the most promising candidate disease‐related gene associated with lung cancers." (PMID 32130794, 2020).
lung carcinoma (continued). "Both SOX2 promoter methylation and air pollution have been associated with lung cancer risk." (PMID 30867047, 2019). "Another study on lung cancer indicated the association of SOX2 with lymphatic metastasis." (PMID 31244283, 2019). "SOX2 has been linked to cancer hallmarks, promoting cell proliferation in breast, pancreatic, prostate and cervical cancers, as well as evading apoptosis in prostate, gastric and lung cancers." (PMID 28678184, 2017). "In line with these facts, SOX2 protein expression was shown to be an independent marker for worse outcome in early stage lung adenocarcinoma and to associate with tumor aggression and higher grade in lung cancer." (PMID 24940116, 2014). "However, the function and underlying mechanism of SOX-2 in carcinogenesis of lung cancer are still elusive." (PMID 23349823, 2013). "Therefore, Sox2 and Msi2 have poor diagnostic specificity in lung cancer." (PMID 23683495, 2013). "Treatment of the 3D organoid cell population with SM-3 resulted in a significant reduction in the levels of stem cell markers (CD133 and CD44) and stem cell transcription factors (OCT-4 and SOX2) in lung cancer organoids." (PMID 40287470, 2025). "In the KRAS-driven lung squamous cancer, enforced expression of SOX2 and/or loss of NKX2-1 leads to an increased TANs and promotes lung cancer tumorigenesis." (PMID 39806421, 2025). "α6β4 integrin epigenetically upregulates the expression of the stemness marker SOX2 through histone acetylation at the Sox2 promoter site, thereby conferring cisplatin resistance in lung cancer cell lines H520 and SBC5." (PMID 40243917, 2025). "To further validate this relationship, we overexpressed SLC16A4 in lung cancer cell lines, A549 and H1299, and observed a marked reduction in SOX2 expression, as assessed by qPCR." (PMID 40867526, 2025). "In lung cancer, for instance, SOX2 can activate SLC7A11 expression, enhancing resistance to ferroptosis and increasing tumor aggressiveness and drug resistance." (PMID 41330917, 2025). "In support of this, several meta-analyses have shown that SOX2 expression in non–small cell lung cancer (NSCLC) and esophageal squamous cell carcinoma (ESCC) correlates with better survival outcomes." (PMID 40227667, 2025). "At the same time, cell therapy with rCD8+ T-cells of the spleen has an inhibitory effect on lung cancer cells and CSCs expressing Sox2 and markers Axl, CD117, EGF, PD-L1 and PD-1." (PMID 38664641, 2024). "Following this, it was discovered that inhibiting Exportin 1 through the downregulation of SOX2 is capable of suppressing NE differentiation in both prostate and lung cancers." (PMID 38543137, 2024). "In human lung cancer tissues, the overexpression of SOX2 and SF3B1 enhances cell resistance to ferroptosis and correlates positively with SLC7A11 expression." (PMID 39624080, 2024). "CDK1 can interact with the stemness marker SOX2 protein and positively regulate the stemness of lung cancer cells." (PMID 38577615, 2024). "It has been demonstrated in mice that SOX2 overexpression results in widespread epithelial hyperplasia and, ultimately, lung carcinoma." (PMID 39355533, 2024).
lung carcinoma (continued). "It was shown that in lung cancer SOX2 down-regulation promotes mesenchymal phenotype and mediates resistance of tumor cells to anti-cancer drugs." (PMID 39175042, 2024). "In lung cancer, SOX2 interacts with HDAC1 to inhibit SOX9 expression, while inhibition of HDAC1 increases SOX9 expression." (PMID 39372390, 2024). "These exosomes were subsequently loaded with SOX2 siRNA through electroporation, effectively silencing SOX2 expression in lung cancer cells and diminishing the stemness of cancer stem cells." (PMID 39204374, 2024). "The tLyp-1-Lam2b-siSOX2 exosomes were efficiently taken up by lung cancer cells, which led to effective knockdown of the SOX2 gene and decreased the stem cell population of lung cancer cells (CD44+/CD24− cells)." (PMID 39355533, 2024). "These aggregated N2-neutrophils secrete miR-4466, which promotes the BM of metastatic lung cancer cells through the SKI/SOX2/CPT1A axis." (PMID 39364322, 2024). "CBP/p300 was reported to promote the transcriptional activation of Sox2 by regulating its acetylation in lung cancer." (PMID 38473392, 2024). "In a previous research report, VNP20009 carrying Sox2 shRNA constructs targeted lung cancer cells and silenced the Sox2 gene, effectively inhibiting tumor growth in heterotransplanted lung cancer mice." (PMID 38372808, 2024). "Recent studies have demonstrated that interaction and phosphorylation of SOX2 by CDK1 positively regulate stemness in lung cancer, and CDK1 phosphorylation of both HIF-1α and EZH2 promotes tumor cells survival and proliferation." (PMID 37189841, 2023). "A bioinformatics study revealed that CDK1 stimulates the stemness of lung cancer cells by the interaction with SOX2 and that increased CDK1 expression shows relationship to lower overall survival in patients suffering from lung cancer." (PMID 37808164, 2023). "Analysis of primary tumors reveals a correlation between chromatin accessibility at this cluster and SOX2 overexpression in breast and lung cancer patients." (PMID 37738673, 2023). "Although the role of SOX-2 in lung cancer has been determined as a result of clinical and preclinical studies." (PMID 37259369, 2023). "The correlation of SMO, GLI1, and SOX2 expression with poor prognosis in lung cancer has been demonstrated." (PMID 37149646, 2023). "In lung cancer, the expression of pluripotent stem cell transcription factors Oct-4, Sox-2, and c-Myc, which are involved in the enrichment process of tumor stem cells induced by cisplatin, is increased." (PMID 37089712, 2023). "We have demonstrated that SOX2 can upregulate GLI1 expression, and SOX2-targeted intervention abolishes GLI1-mediated stemness of lung cancer cells." (PMID 37149646, 2023). "In lung cancer and prostate cancer, survivin was a key downstream molecule of SOX2 in anti‐apoptosis." (PMID 37658588, 2023). "In genomic alterations in lung cancer, SOX-2 is considered a potential target for therapeutic intervention." (PMID 37259369, 2023). "Overexpression of BCAT1 in lung cancer cells led to a dramatic downregulation of α-KG and resulted in activation of SOX2." (PMID 37460470, 2023). "In this study, the diagnostic performance of HOXA9 gene promoter methylation, SOX2 gene and HV2 gene CNV were evaluated for detection of lung cancer." (PMID 37038139, 2023). "There are also studies in the literature reporting that SOX-2 is overexpressed and acts as an oncogene in lung cancer." (PMID 37259369, 2023). "SOX2 is a downstream target of GLI1, and the GLI1/SOX2 axis contributes to stemness-related EGFR resistance in lung cancer cells." (PMID 37149646, 2023). "RT-qPCR demonstrated that GLI1 or SOX2 overexpression remarkably stimulated the SMO/GLI1/SOX2OT/SOX2 axis in lung cancer cells." (PMID 37149646, 2023).